IL17A (interleukin 17A)
Diseases named in the same sentence as IL17A in open-access papers (continued):
Sharing a sentence is not in itself a finding about the gene and the disease.
periodontitis (continued). "Salivary IL-8 levels and IL-17A detection rates were significantly elevated in periodontitis." (PMID 41708693, 2026). "Semi‐quantitatively, using WB, we found overexpression of the IL‐23/IL‐17A axis and its receptors in the GT of patients with periodontitis, which coincides with several authors, including the expression of IL‐23R, which we had previously found to be decreased by the ELISA method." (PMID 41536464, 2026). "Of note, other studies have found that, despite the elevated IL-17A levels in periodontal tissues of patients with periodontitis, plasma IL-17A levels may actually be reduced." (PMID 40248692, 2025). "IL-17A-mediated iron metabolism prompted ferritin expression in osteoblasts, eventually bolstering osteogenic differentiation and alveolar bone repair via autophagy activation in murine periodontitis models." (PMID 40066457, 2025). "Additionally, STAT3 phosphorylation was activated in OSCC with periodontitis but declined upon γδ T cell inhibition, suggesting a pivotal role of γδ T cells in tumor progression via IL-17A and STAT3 signaling." (PMID 40924302, 2025). "A periodontitis model was established in mice with conditional deletion of Stat3 in Th17 cells (Stat3fl/fl; Il17a-CreERT2, cKO) and wild type (Stat3fl/fl, WT) mice via injection of Porphyromonas gingivalis lipopolysaccharide (P. gingivalis LPS) into gingival sulcus." (PMID 40933993, 2025). "Furthermore, serum IL-17A levels in RA patients with periodontitis are significantly higher than those in periodontitis patients without systemic disease." (PMID 37623290, 2023). "IL-17A is secreted by a variety of innate and adaptive immune cells and activates a series of inflammatory cascade responses that mediate the onset and development of periodontitis and systemic inflammatory diseases." (PMID 37623290, 2023). "Therefore, this section focuses on the pathogenesis of systemic chronic inflammatory diseases related to IL-17A and induced by oral dysbiosis in periodontitis." (PMID 37623290, 2023). "However, in the present study, the IL-6 and IL-17A production during the 2 years of orthodontic treatment was lower than those detected during previous periodontitis." (PMID 36902236, 2023). "However, the periodontitis-associated TH17 cells proliferation requires of IL-6 and IL-23 to increase the production of IL-17A." (PMID 36967976, 2023). "Previous publications highlighted the role of IL17A in periodontitis." (PMID 36769650, 2023). "The results of previous studies suggest that IL-17A and IL-17B isoforms may play the most important role in the development of periodontitis." (PMID 37510729, 2023). "Finally, we demonstrated that IL-17A was required for the periodontitis salivary microbiota to exacerbate ischemic stroke." (PMID 35663549, 2022). "More research are needed to determine whether IL-17A inhibitors can be used topically to treat periodontitis and at what development stage of periodontitis that IL-17A inhibitors should be used." (PMID 35371044, 2022). "In our study, the increased expression of RORγt may explain the reason of up-regulated IL-17A induced by periodontitis salivary microbiota." (PMID 35663549, 2022). "Furthermore, it has been reported that the expression level of IL-17A mRNA in gingival tissue of patients with chronic periodontitis was higher than that of patients with gingivitis." (PMID 35371044, 2022). "A study performed by Satoru showed that IL-17A may promote the progression of periodontitis through proinflammatory cytokine production." (PMID 35397550, 2022). "IL-17A plays a protective and destructive role in the progression of chronic periodontitis." (PMID 35371044, 2022). "During periodontitis, Treg lymphocytes show a reduced Foxp3 expression and, instead, produce IL-17A and RANKL; thus, making the inflammatory milieu highly enriched in inflammatory cytokines like IL-6, pivotal in dictating Treg lymphocyte fate in periodontal lesions." (PMID 34220811, 2021).
periodontitis (continued). "IL-17A is considered the main cytokine in the pathogenesis of periodontitis." (PMID 34557201, 2021). "Both IFN-γ and IL-17A expression were dramatically increased in periodontitis patients." (PMID 34381457, 2021). "Salivary concentrations of IL-6, and IL-17A were increased in SLE patients with periodontitis." (PMID 33861790, 2021). "TREM-1 regulates the IL-17A-RANKL/OPG axis and bone loss in experimental periodontitis." (PMID 34445604, 2021). "Moreover, these cells exhibit an inflammatory phenotype indicated by enhanced production of IFN-γ and IL-17A in periodontitis." (PMID 34381457, 2021). "IL-17A is increased in periodontitis and positively correlated with disease severity." (PMID 34381457, 2021). "Th17/Treg imbalance is involved in periodontitis development, as indicated by enhanced Th17 response with increased IL-17A production and suppressed anti-osteoclastogenic function of Treg, which is also associated with exacerbated periodontitis during pregnancy." (PMID 34869062, 2021). "The present study aimed to investigate the salivary and serum levels of inflammatory cytokines IL-17A and IL-18 in subjects with different glycemic and periodontal status in order to clarify the interrelationship among these cytokines, type 2 DM, and periodontitis." (PMID 32053656, 2020). "IL-17A has been suggested to contribute to the pathogenesis of periodontitis in many ways." (PMID 32053656, 2020). "In addition to the potential role of IL-17A and IL-18 in the local involvement of periodontitis, a systemic role of these cytokines and interactions with DM has also been recognized." (PMID 32053656, 2020). "Salivary IL-17A levels may reflect the local role of this cytokine in the pathogenesis of periodontitis, whereas serum IL-17A levels may reflect the systemic role in a variety of conditions." (PMID 32053656, 2020). "Our study revealed that salivary IL-17A levels were firmly associated with the severity of periodontitis without the influence of glycemic status." (PMID 32053656, 2020). "A recent study has revealed that IL-35 produced by regulatory T cells might block the development of periodontitis by reducing IL-17A-induced IL-6 and IL-8 expression." (PMID 33327639, 2020). "Tregs derived from mice with experimental periodontitis showed reduced Foxp3 expression, increased Th17-related gene expression, particularly IL-17A, and a reduced capacity to suppress osteoclastogenesis, thus indicating that periodontal inflammation affected Treg immunosuppressive capacity." (PMID 33149125, 2020). "This study also demonstrated the benefit of saliva specimen in periodontal diagnostics since we found that salivary IL-17A levels could reflect the severity of periodontitis." (PMID 32053656, 2020). "Therefore, this study was aimed to investigate the local and systemic role of IL-17A and IL-18 by measuring salivary and serum levels in subjects with type 2 DM and periodontitis." (PMID 32053656, 2020). "Interestingly, exFoxp3TH17 cells in periodontitis-induced mice had much higher expression levels of effecter molecules such as Rorc, Il17a, Il17f, and Tnfsf11 than conventional TH17 cells." (PMID 29453398, 2018). "IL-6 induced by IL-17F or IL-17A may play a potential feedback loop in the pathogenesis of chronic periodontitis." (PMID 29670909, 2018). "Periodontitis-induced Il17a expression in the oral mucosa was completely inhibited in Il6–/– mice." (PMID 29453398, 2018). "Though our previous studies have focused on the expression level of Th17 associated cytokines in periodontitis patients, we still do not know the expression level of IL-17A+IL-17F− and/or IL-17A−IL-17F+ Th17 cells in CP patients compared to healthy controls." (PMID 25525302, 2014). "This study indicates that both the IL-17A+IL-17F− and IL-17A−IL-17F+ Th17 cells may be involved in pathogenesis of periodontitis." (PMID 25525302, 2014).
periodontitis (continued). "However, to the extent of our knowledge, there are still less reports focused on the correlation between (IL-17A+ and/or IL-17F+) Th17 cells and periodontitis." (PMID 25525302, 2014). "Therefore, the present clinical study was designed to detect the expression levels of (IL-17A+ and/or IL-17F+) Th17 cells in periodontitis patients." (PMID 25525302, 2014). "Therefore, this is the first study reporting elevated levels of IL-17A+IL-17F− and IL-17A−IL-17F+ Th17 cells in chronic periodontitis." (PMID 25525302, 2014). "Taken together, this clinical study indicated that IL-17A+ and/or IL-17F+ positive Th17 may participate in the periodontitis pathogenesis." (PMID 25525302, 2014). "In contrast, when evaluating IL-17A, we detected a significant difference in the distribution of genotypes for the polymorphism IL-17A G197A comparing subjects with and without periodontitis." (PMID 23304063, 2012). "The aims of this study were (i) to assess whether the salivary IL-1β, IL-17A, RANK-L and OPG levels have the potential to discriminate between the mild and severe periodontitis conditions; and (ii) to enable diagnostic/prognostic actions to differentiate between distinct levels of the disease." (PMID 36769650, 2023). "Taken together, oral dysbiosis could influence the bidirectional relationship between periodontitis and DM; moreover, IL-17A expression resulting in oral floral changes induced by increased systemic inflammation may increase insulin resistance and promote hyperglycemia." (PMID 37623290, 2023). "Therefore, alterations in IL-17A levels induced by periodontitis may systemically affect synovial tissue destruction and influence RA pathogenesis." (PMID 37623290, 2023). "Therefore, IL-17A has an important role in the progression of periodontitis." (PMID 37623290, 2023). "Finally, we tested whether IL-17A was required for periodontitis salivary microbiota to exacerbate ischemic stroke." (PMID 35663549, 2022). "Periodontitis salivary microbiota increased IL-17A-producing immune cells in small intestine, and provoked migration of IL-17A-producing cells from the gut to the brain, which might initiate the early inflammatory cascade and ultimately exacerbated ischemic stroke." (PMID 35663549, 2022). "IL-17A may be the link between PsO and periodontitis, but there is no direct evidence that there is a causal relationship between them, which needs to be further clarified." (PMID 35371044, 2022). "It has been found that interleukin-17A (IL-17A) secreted by various innate and adaptive immune cells can activate a series of inflammatory cascade reactions, which mediates the occurrence and development of periodontitis and related systemic chronic inflammatory diseases." (PMID 35371044, 2022). "Given ILCs are an important source of IL-17A and IFN-γ, which have been shown to be associated with periodontitis susceptibility in a large quantity of clinical studies, we next sought to determine whether ILCs from periodontitis patients could produce more inflammatory cytokines." (PMID 34381457, 2021). "Indeed, we observed ILC3s produced more IL-17A in periodontal ligament from periodontitis patients." (PMID 34381457, 2021). "This could explain why salivary IL-17A is upregulated in subjects with periodontitis." (PMID 32053656, 2020). "However, one study showed higher serum IL-17A levels in patients with chronic periodontitis." (PMID 32053656, 2020). "Moreover, relative IFN-γ, IL-17A, and T-bet mRNA levels were also significantly higher in patients with chronic periodontitis compared to controls, suggesting that Th17 and Th1 cells might be involved in the pathogenesis of chronic periodontitis." (PMID 31416146, 2019). "Indeed, genetic polymorphisms in IL-17A have been suggested to enhance the impact of periodontitis on type I diabetes, indicating that a failure of adequate host immunity during periodontitis can lead to worsening of other non-oral diseases." (PMID 31293577, 2019).
periodontitis (continued). "In vitro, IL-17E suppressed IL-17A and P. gingivalis induced chemokine-expression by inhibiting phosphorylation of the NF-kB p65 subunit, which indicated that in the pathogenesis of periodontitis the serum IL-17A-IL-17E ratio might be a marker of disease severity while IL-17E is opposing IL-17A." (PMID 30837987, 2019). "Furthermore, elevated IL-17A levels were detected in GCF of patients with periodontitis." (PMID 30837987, 2019). "Interestingly, in this series, and unlike the other pro-inflammatory cytokine ratios, the GMCSF/IL17A ratio had significantly lower values in the periodontal patients, representing the first evidence of the impact of this ratio in the pathogenesis of periodontitis." (PMID 30573746, 2018). "However, other investigations showed that Th17 cells may produce IL-17A to play protective role by neutrophils recruitment to destructed area in periodontitis lesions." (PMID 25525302, 2014). "Studies have reported that RANKL is upregulated in patients with periodontitis, and one of the pathways for RANK/RANKL activation is the IL‐23/IL‐17A axis, which plays an important role in the immunopathology of periodontitis." (PMID 41536464, 2026). "Numerous studies have confirmed that individuals with periodontitis exhibit higher serum levels of inflammatory markers such as IL-1β, TNF-α, IL-17A, IL-6, and lower levels of the anti-inflammatory cytokine IL-10 compared to healthy controls." (PMID 40732209, 2025). "This led to the following research question: What is the effect of closed-field scaling and root planning on serum levels of IL-1β, IL-4, IL-6, IL-8, IL-10, IL-12p70, IL-17A, VEGF, and TNF-α in patients with periodontitis and high blood pressure?" (PMID 40002786, 2025). "In pooled chronic/aggressive periodontitis, GCF IL-23 showed a downward trend for >6 weeks, and in generalised aggressive periodontitis, GCF IL-23 trended down at >3 months alongside IL-17A." (PMID 41375728, 2025). "Systemic IL17A decreases were more evident in generalized aggressive periodontitis than in chronic periodontitis, whereas GCF IL17A reductions were consistent across phenotypes in the ~6–8-week window." (PMID 41375728, 2025). "Here, we utilized the murine ligature-induced model of periodontitis (LIP) and IL-17A fate reporter mice (Il17aCreR26ReYFP) to examine the functional capabilities of Th17 cells during periodontitis." (PMID 38819409, 2024). "IL-17A also stimulates fibroblasts, epithelial cells, and endothelial cells to produce RANKL, MMP, PGE2, and chemokines to promote the progression of periodontitis." (PMID 38919613, 2024). "Elevated concentrations of IL-17A have been identified in the serum, gingival crevicular fluid (GCF), and saliva of individuals with periodontitis." (PMID 39215253, 2024). "In RA and periodontitis, adaptive and innate immune cells promote the release of proinflammatory cytokines (TNF-α, IL-6, IL-17A, IL-1β, RANKL), which have an important role in establishing and maintaining inflammation." (PMID 37217496, 2023). "There was a higher prevalence of stage III periodontitis and severe OSA, as well as higher levels of periodontal parameters (PI and BOP), and expression of IL-1β and IL-6 in saliva and IL-6, IL-17A, and IL-33 in GCF, in patients with periodontitis and OSA." (PMID 36967976, 2023). "BBR effectively reduced local and systemic inflammation in a periodontitis rat model by lowering TNF-α and IL-17 production and the number of IL-17A+ cells in the alveolar bone." (PMID 37317243, 2023). "IL-17A can also induce osteoblasts to secrete RANKL to participate in osteoclast differentiation, mediating alveolar bone absorption in patients with periodontitis." (PMID 35371044, 2022). "Considering the available immunological data, MMP‐8, IL‐17A, and INF‐γ seem to be promising biomarkers for an interaction between IBD and periodontitis and possible role of Th17 cells deserves further research." (PMID 33690955, 2022).
periodontitis (continued). "It has also been confirmed that interleukin-17A (IL17A), which is secreted by various innate and adaptive immune cells, can mediate the occurrence and progression of periodontitis." (PMID 36703983, 2022). "Our data demonstrated that, with the expansion of IL-17+ γδ T cells and increased expression of IL-17A, the STAT3 phosphorylation was also activated in both the early stage and late stage of OSCC with periodontitis." (PMID 36000726, 2022). "The populations of TNF-α- or IL-17A-producing memory CD4+ and CD8+ T cells were significantly higher in the regional lymph nodes of HFD-fed mice with periodontitis than in those of mice fed a NCD." (PMID 35069547, 2021). "Regarding intestinal tissue analyses, higher levels of IL-1β, IL-4, IL-6, IL-17A, IL17F, IL-21, IL-31, IL-33 and soluble CD40 ligand (sCD40L) were found in patients having IBD activity and periodontitis." (PMID 34501547, 2021). "Together, these data suggest that both ILC1s and ILC3s promote periodontal inflammation during periodontitis through secreting inflammatory cytokines IFN-γ and IL-17A." (PMID 34381457, 2021). "We found significantly more TNF-α- or IL-17A-producing CD4+ and CD8+ T cells in the regional lymph nodes of mice with ligature-induced periodontitis than in control lymph nodes." (PMID 35069547, 2021). "Regarding intestinal tissue analyses, higher levels of IL-1β, IL-4, IL-6, IL-17A, IL17F, IL-21, IL-31, IL-33 and sCD40L were found in patients with IBD and periodontitis." (PMID 34501547, 2021). "Collectively, these data suggest that ILC1s and ILC3s promote local inflammatory responses in periodontal ligament tissue of periodontitis through producing inflammatory cytokines of IFN-γ and IL-17A." (PMID 34381457, 2021). "High levels of IL-17A, IL-17F IL-22, IL-25, IL-33, IL-10 and INF-y were found in gingival biopsies compared with intestinal biopsies from patients with IBD and periodontitis." (PMID 34501547, 2021). "Pivotal inflammatory cytokines in periodontitis, namely IL-1β, IL-6, TNF-α and IL-17A, mediate both periodontal inflammation and alveolar bone resorption." (PMID 31848404, 2019). "Periodontitis is a prevalent chronic inflammatory disease due to the host response (IL-1β, IL-6, TNF-α and IL-17A) to oral bacteria such as Porphyromonas gingivalis." (PMID 31848404, 2019). "In the present study, other ratios such as IL17A/IFNgamma, IL17A/IL2, IL17A/IL3 and IL17A/IL4 had significantly higher values in the periodontal patients, reflecting their impact on chronic periodontitis." (PMID 30573746, 2018). "Furthermore, local administration of these CD73+ Treg‐derived EVs in a murine periodontitis model reduced activated CD4+ T cell infiltration, decreased IL‐17A and RANKL expression, and attenuated osteoclast‐mediated alveolar bone loss." (PMID 40620009, 2025). "Although most have concluded that IL‐23 and IL‐17A are elevated in patients with periodontitis unlike healthy subjects, some authors have disagreed or have not observed significant differences." (PMID 39887950, 2025). "Serum IL-23 findings were mixed: decreased levels were found in a generalised aggressive periodontitis cohort at ~3 months in concert with IL-17A, and no marked change was seen at ~6 months in a mixed chronic/aggressive cohort." (PMID 41375728, 2025). "Serum IL-17A decreased by ~1 month in chronic periodontitis (with/without type 2 diabetes) and by ~6 months in generalized aggressive periodontitis." (PMID 41375728, 2025). "We also observed that the patients with periodontitis III/IV had higher mean values of IL-17A compared to the periodontally healthy controls and the patients with periodontitis I/II, albeit without reaching statistical significance." (PMID 36769650, 2023).